IRX3 (iroquois homeobox 3)
Diseases named in the same sentence as IRX3 in open-access papers (continued):
Sharing a sentence is not in itself a finding about the gene and the disease.
Obesity (continued). "For example, obesity-linked non-coding SNPs in the fat mass and obesity-associated gene (FTO) are spatially connected [i.e., they are physically interacting in a manner, which can be captured by proximity-ligation techniques (e.g., 4C-seq)] to promoters at the Iroquois homeobox 3 (IRX3) gene." (PMID 26191039, 2015). "For instance, in comparison to FTO, ZFHX3 has approximately 1 million base-pairs closer to Iroquois homeobox protein 3 (IRX3), which is known to mechanistically interact with the genetic variation of FTO to influence obesity and related metabolic disorders." (PMID 39060932, 2024). "For example, there is evidence for eQTLs (for IRX3 and FTO), chromatin looping, TF motifs, DNase I hotspots, and histone mark broadPeaks for rs1421085, a SNP previously identified for obesity." (PMID 38167104, 2024). "Their studies confirm that variants in multiple enhancers within FTO obesity-associated regions regulate the expression of multiple genes (IRX3 and IRX5) in at least two obesity-relevant tissues (adipose and brain)." (PMID 35205324, 2022). "In contrast, a recent study demonstrated that partial (approximately 50%) inhibition of endogenous hypothalamic IRX3 expression reduced thermogenesis in peripheral BAT and increased diet-induced body mass gain, thereby exacerbating obesity." (PMID 33776928, 2021). "In a recent report, another line of Irx3 knockout mice (Irx3Δ/Δ) generated by CRISPR editing was also shown to be lean and protected against diet-induced obesity." (PMID 34795556, 2021). "Furthermore, it is unclear what effect IRX3 expression would have on breast cancer risk and whether any effect would be independent of the risk attributed to obesity alone." (PMID 33785833, 2021). "This study knocked out bama pig IRX3 using CRISPR/Cas9 gene editing technology to explore the relationship between IRX3 and body weight and obesity in pig." (PMID 32192102, 2020). "The proposed causal allele was shown to alter an ARID5B repressor motif, leading to activation of the distant IRX3 and IRX5 in adipocyte precursor cells, and pro-obesity consequences for adipocyte thermogenesis regulation [23•]." (PMID 28758174, 2017). "Targeted deletion of Irx3 in mice results in reduced body size and resistance to HFD-induced obesity, whereas mice heterozygous for a deletion in Ftm (also Rpgrip1l) results in increase of body-weight." (PMID 25242086, 2014). "For instance, an obesity-related SNP found in the intron of the FTO gene was found to influence the process of adipocyte browning by regulating the activity of IRX3 and IRX5, rather than directly impacting FTO itself." (PMID 36837926, 2023). "For example, macronutrient–gene interactions might affect obesity phenotypes, potentially by regulation of FTO and IRX3 gene expression." (PMID 36979984, 2023). "Actually, this particular SNP was reported to increase expression of IRX3 and IRX5 through 3D chromatin effects during preadipocyte differentiation, thereby enhancing the formation of energy-storing white adipocytes, lipid storage, and obesity development." (PMID 35051171, 2022). "Moreover, lifestyle modification appeared to have an impact on obesity through changes in the expression of the FTO and IRX3 genes." (PMID 34038448, 2021). "As most clinical data have illustrated that the risk alleles of FTO are associated with increased energy intake, our data highlight hypothalamic postnatal neurogenesis regulated by IRX3 and IRX5 as a potential mechanism affecting leptin response in human obesity." (PMID 34795556, 2021). "The status of FTO in obesity alone does not reveal an effect, especially when the level of IRX3 is changed through FTO knockdown or overexpression." (PMID 33162550, 2020). "For example, although FTO was reported as a susceptibility gene for obesity, the effector genes whose expression levels were influenced by the significantly associated SNPs were not FTO but Iroquois Homeobox 3 (IRX3) and IRX521." (PMID 30643196, 2019).
Obesity (continued). "Lifestyle modification may exert its effects on obesity through changes in the expression level of the FTO and IRX3 genes." (PMID 31126299, 2019). "In addition, it was reported that the FTO gene realizes its effect on body composition and obesity in interaction with other genes, such as FTM (RPGRIP1L) and Irx3, which are localized near it." (PMID 31810473, 2019). "Although the strong association between FTO variations and obesity has been continuously reported, the genetic defects of the IRX3 gene per se on obesity have not been clarified until now." (PMID 28988979, 2017). "A recent study indicates that the obesity association of the first intron does not imply FTO as the causal gene, but IRX3 located downstream on the same chromosome which is regulated by the first intron of FTO." (PMID 26828654, 2016). "The fact that the obesity-associated FTO SNPs are intronic has led to the notion that the SNPs may affect obesity through influencing the expression of genes proximal to FTO in the locus, namely, RPGRIP1L, IRX3, and IRX5." (PMID 26788058, 2015). "Lastly, polymorphisms in FTO are likely to be one of the reasons why obesity characteristics of PCOS patients vary by country and ethnicity, which can affect adipocyte differentiation and function by changing the activity of neighboring genes, including iroquois homeobox-3 (IRX3) and IRX5." (PMID 40410881, 2025). "Furthermore, lifestyle modifications may exert their effects on obesity through changes in the expression of the FTO and IRX3 genes." (PMID 34038448, 2021). "In the human brain, obesity-associated FTO SNPs correlated with higher expression of IRX3, but not FTO, indicating that increased expression of IRX3 may be due to the genetic variation within FTO being responsible for the obesity-associated phenotypes." (PMID 31482095, 2019). "Furthermore, by defining the genes/pathways regulated by Irx3 and Irx5 in RGL-NSCs as well as their interplays with the Notch, Shh and Fgf pathways should unveil new knowledge about postnatal remodeling of the hypothalamus and provide mechanistic insights in NSC biology and obesity." (PMID 34795556, 2021). "Moreover, this study shows that knocking out IRX3 does not favor the survival of pigs, and whether targeted regulation of IRX3 in the treatment of human obesity will also induce severe adverse consequences requires further investigation." (PMID 32192102, 2020). "Regardless of whether the obesity-associated SNP affects FTO expression levels, these studies have clearly proven an important role of FTO in the regulation of body weight, independent of IRX3, IRX5, and RPGRIP1L." (PMID 26788058, 2015). "IRX3 and IRX5 have emerged as a strong link between the non-coding genetic variations of the FTO gene and obesity." (PMID 34795556, 2021). "Finally, IRX3, which was already described as a negative and positive regulator of the development of thermogenic adipocytes, was also among the genes kept lowly expressed in DN and FTO T/T adipocytes, but became higher expressed in the adipocytes with the obesity-risk genotype." (PMID 32316277, 2020). "Using 4C-seq, investigators showed that enhancers located within an intron of the FTO gene and harboring obesity and T2D GWAS-identified SNPs do not interact with the FTO promoter but instead interact with the IRX3 gene which is located 500 Kb downstream." (PMID 26719772, 2015).
acute myeloid leukemia (7 papers, 2018 to 2024). Acute myeloid leukemia (AML) is a group of neoplasms arising from precursor cells committed to the myeloid cell-line differentiation. "Iroquois transcription factor gene IRX3 is highly expressed in 20–30% of acute myeloid leukemia (AML) and contributes to the pathognomonic differentiation block." (PMID 37539037, 2023). "Analysis of public profiling data from acute myeloid leukemia (AML) patients revealed aberrant activity of IRX1 in addition to IRX3 and IRX5, indicating an oncogenic role for these TALE homeobox genes when deregulated." (PMID 35328612, 2022). "In contrast, sister homeobox genes IRX2, IRX3 and IRX5 are aberrantly activated in the corresponding malignancies acute myeloid leukemia (AML) and B-cell progenitor acute lymphoid leukemia." (PMID 39689089, 2024). "In acute myeloid leukemia (AML), increased expression of IRX3 was also observed." (PMID 36980893, 2023). "Using the myeloid TALE-code, we have recently detected physiological activity of TALE homeobox gene IRX1 exclusively in megakaryocyte erythroid progenitors (MEPs) during early myelopoiesis, and aberrant expression of IRX1, IRX3 and IRX5 in particular subtypes of acute myeloid leukemia (AML)." (PMID 36233173, 2022). "On the other hand, the closely related homeobox genes IRX2, IRX3 and IRX5 are aberrantly expressed in subsets of BCP-ALL and acute myeloid leukemia (AML) patients and cell lines." (PMID 39689089, 2024). "Accordingly, screening for aberrant IRX gene activities in acute myeloid leukemia (AML) revealed overexpression of IRX1, IRX3 and IRX5 in subsets of patients, identifying these genes as oncogenes for this type of malignancy." (PMID 36833225, 2023). "Moreover, aberrant expression of IRX homeobox genes IRX1, IRX2, IRX3 and IRX5 has been detected in hematopoietic malignancies, including B-cell precursor acute lymphoblastic leukemia (BCP-ALL), T-cell ALL, and some subtypes of acute myeloid leukemia (AML)." (PMID 36833225, 2023).
acute lymphoblastic leukemia (5 papers, 2018 to 2024). Leukemia with an acute onset, characterized by the presence of lymphoblasts in the bone marrow and the peripheral blood. "IRX3 is also strongly expressed in up to 50% of cases of human T-acute lymphoblastic leukemia, and its forced expression in normal T cell precursors impedes their differentiation in vitro." (PMID 37539037, 2023). "To provide a more comprehensive evaluation of the role of IRX3 in human acute leukemia, we analyzed published expression datasets from patients with acute lymphoblastic leukemia (ALL)." (PMID 29346763, 2018). "In B-acute lymphoblastic leukemia (B-ALL), high IRX3 expression was detected in 116 of 563 cases (21%) in the MILE cohort." (PMID 29346763, 2018). "In leukemia, IRX3 is overexpressed in about 30% of cases of AML, 50% of T-acute lymphoblastic leukemia, and 20% of B-acute lymphoblastic leukemia, while its expression is almost undetectable during normal hematopoiesis and in mature blood cells." (PMID 37539037, 2023). "Finally, the mechanism that we propose for the activation of IRX3 in AML cannot explain how this transcription factor gene is so highly expressed in around 50% of cases of T-acute lymphoblastic leukemia, where expression of FTO-lncAML is not observed." (PMID 37539037, 2023). "Furthermore, we identified aberrant expression of IRX2, IRX3 and MEIS1 in patients with B-cell precursor acute lymphoblastic leukemia (BCP-ALL) which originates from early B-cell progenitors." (PMID 36233173, 2022).
type 2 diabetes (5 papers, 2020 to 2024). "We find evidence for a causal effect of increased expression of IRX3 in pancreatic islets on increased risk of type 2 diabetes (OR = 1.16, 95% CI = [1.08, 1.25], p value = 4.4 × 10−5, F stat = 16.7)." (PMID 37433298, 2023). "These predictions were validated by transgenic reporter assays and implicated IRX3 in the development of type 2 diabetes and obesity for the first time." (PMID 31616042, 2020).
leukemia (4 papers, 2018 to 2023). A malignant (clonal) hematologic disorder, involving hematopoietic stem cells and characterized by the presence of primitive or atypical myeloid or lymphoid cells in the bone marrow and the blood. "Irx3 is also associated with malignancies in humans, such as particular subtypes of leukemia, where it may influence T cell maturation checkpoints." (PMID 37535648, 2023). "Indeed, in leading-edge analyses, there was a highly significant association of higher IRX3 expression in human HOXA9+ AML with greater repression of IRX3-repressed genes identified in murine leukemias." (PMID 29346763, 2018). "Together these data demonstrate that IRX3 expression impedes normal T-progenitor differentiation in vitro and induces T-lineage leukemias in vivo." (PMID 29346763, 2018). "Hoxa9/IRX3 AML cells induced leukemias in secondarily transplanted recipients, and high-level IRX3 expression was readily detected in Hoxa9/IRX3 AML BM cells." (PMID 29346763, 2018). "At least in AML, IRX3 misexpression is found in both bulk and the putative stem cell compartments, suggesting functional contribution throughout the leukemia clone." (PMID 29346763, 2018). "Murine Hoxa9/FOXC1 leukemias also exhibited shortened latency versus Hoxa9/MTV leukemias, in contrast to the latencies observed for Hoxa9/IRX3 leukemias." (PMID 29346763, 2018). "Gene set enrichment analysis (GSEA) confirmed that co-expression of IRX3 with Hoxa9 led to repression of a mature myeloid lineage program in KIT+Gr1+ leukemia cells, in keeping with morphologic analysis." (PMID 29346763, 2018). "High-level expression of IRX3 is frequent in human leukemia, is sufficient for immortalization of murine hematopoietic stem and progenitor cells, and when co-expressed with Hoxa9 in a murine model substantially deepens the level of differentiation block observed in the resulting AMLs." (PMID 37539037, 2023). "To determine whether co-expression of IRX3 influences leukemia cell differentiation in vivo, we transplanted Hoxa9/IRX3 and Hoxa9/MTV double-transduced BM HSPCs into irradiated congenic recipients." (PMID 29346763, 2018). "Analysis of 8,954 protein-coding genes that passed threshold criteria (i.e., expression >0.5 reads per kilobase per million mapped reads [RPKM] in at least one sample) revealed that 197 were upregulated and 403 downregulated by at least 2-fold in Hoxa9/IRX3 versus Hoxa9/MTV leukemias." (PMID 29346763, 2018). "Likewise, the set of genes anti-correlated with the LSC maintenance program (i.e., associated with differentiated leukemia cells, downstream of the LSC) was strongly repressed in Hoxa9/IRX3 versus Hoxa9/MTV AML cells." (PMID 29346763, 2018). "Screening of RNA-seq data from 100 leukemia/lymphoma cell lines showed overexpression of IRX1, IRX3, and IRX5 in megakaryoblastic and myelomonocytic AML cell lines, chosen as suitable models for studying the regulation and function of these homeo-oncogenes." (PMID 35328612, 2022). "To evaluate the consequences for the transcriptome of co-expression of IRX3 with Hoxa9, we performed RNA sequencing of flow-sorted KIT+Gr1+ leukemia cells recovered from the BM of sick mice, three from each cohort." (PMID 29346763, 2018). "Three of six IRX3-expressing HSPC recipients developed donor-derived lymphoid leukemia; in two cases, the leukemia was T-lineage, and mice exhibited splenomegaly and near total BM involvement." (PMID 29346763, 2018).
brain tumor (3 papers, 2009 to 2025). "IRX3 promotes cell proliferation, colony formation, migration, and invasion in vitro and brain tumor growth in vivo." (PMID 41436436, 2025). "IRX3 is epigenetically inactivated by methylation in CpG islands in brain tumours and prostate cancer." (PMID 19826427, 2009). "A methylated CpG island was detected in exon 2 of the IRX3 locus, rather than in the promoter, and is responsible for IRX3 overexpression in brain tumor cells and tissues." (PMID 21333016, 2011).
ventricular fibrillation (3 papers, 2016 to 2023). A disorder characterized by an electrocardiographic finding of a rapid grossly irregular ventricular rhythm with marked variability in QRS cycle length, morphology, and amplitude. "Within the currently described transcriptional regulators of SCN5A expression, only mutations in IRX3 have been associated with ventricular fibrillation." (PMID 35163304, 2022). "Mutations in IRX3 cause ventricular fibrillation, the main cause of sudden cardiac death in humans." (PMID 36818345, 2023). "In addition, a recent study has identified two novel IRX3 mutations in patients with idiopathic ventricular fibrillation and demonstrated that these mutations resulted in impaired transcriptional regulation of Gja515." (PMID 26786475, 2016). "Interestingly, those IRX3 mutations impaired SCN5A expression in in vitro experimental assays, yet the causal contribution to ventricular fibrillation remains unclear." (PMID 35163304, 2022).
colorectal cancer (2 papers, 2023). A primary or metastatic malignant neoplasm that affects the colon or rectum. "Increased expression of IRX3 and IRX5 was found in the transition of intestinal adenoma to colorectal cancer, negatively regulating the DPp/TGF-ß pathway." (PMID 36980893, 2023). "The expression of IRX3 and IRX5 can downregulate TGF-β signaling in human colorectal cancer cells." (PMID 36980893, 2023).
diabetes (2 papers, 2019 to 2023). "Also in the multivariable Cox-regression model for all-cause mortality, IRX3 promoter methylation remained statistically significant along with diabetes and atrial fibrillation, whereas the other clinical parameters did not." (PMID 37697352, 2023).
hepatocellular carcinoma (2 papers, 2017 to 2021). A malignant tumor that arises from hepatocytes. "IRX3 has been suggested as a tumor-promoting gene in several tumors such as hepatocellular carcinoma and may contribute to tumor angiogenesis." (PMID 34769455, 2021). "Moreover, downregulation of miR-377 contributes to IRX3 deregulation in hepatocellular carcinoma." (PMID 28913356, 2017).
Insulin resistance (2 papers, 2010 to 2016). Increased resistance towards insulin, that is, diminished effectiveness of insulin in reducing blood glucose levels. "Moreover, we detected significant associations of adipocyte IRX3 expression with adiponectin and leptin serum levels and with HOMA-IR as a measure of insulin resistance, which were, however, lost after adjustment for BMI SDS and age." (PMID 27560134, 2016). "Independent of BMI, IRX3 expression in adipocytes was significantly related to adipocyte hypertrophy, which may explain subsequent associations with AT inflammation and parameters of insulin resistance." (PMID 27560134, 2016).
lymphoid leukemia (2 papers, 2018 to 2020). A malignant lymphocytic neoplasm of B-cell or T-cell lineage involving primarily the bone marrow and the peripheral blood. "Expression of IRX3 alone was sufficient to immortalize hematopoietic stem and progenitor cells (HSPCs) in myeloid culture and induce lymphoid leukemias in vivo." (PMID 29346763, 2018). "IRX3 was highly expressed in approximately 30% of patients with AML, and high expression of IRX3 alone can perpetuate hematopoietic stem cells and progenitor cells (HSPC) in bone marrow cultures and induce lymphoid leukemia in vivo." (PMID 33304380, 2020). "In keeping with a role for IRX3 in promoting the development of lymphoid leukemias, we found that irradiated congenic mice transplanted with IRX3-expressing KIT+ BM HSPCs developed lymphoid leukemias with incomplete penetrance." (PMID 29346763, 2018). "The observations that HSPCs expressing IRX3 alone were immortalized in myeloid culture, failed to expand significantly in OP9 stromal culture, but generated Hoxa-expressing lymphoid leukemias in vivo reflect the importance of the cellular microenvironment in supporting phenotypic outcome." (PMID 29346763, 2018).